HGF (hepatocyte growth factor)
Diseases named in the same sentence as HGF in open-access papers (continued):
Sharing a sentence is not in itself a finding about the gene and the disease.
lung fibrosis (continued). "On the contrary, it could be shown that HGF, the only known ligand for c-Met, conveys protective effects in different chronic diseases such as liver cirrhosis and lung fibrosis." (PMID 30538805, 2018). "In addition to their immune suppressive properties, MSCs secrete a variety of anti‐fibrogenic proteins and enzymes such as interleukin‐10 (IL‐10), hepatocyte growth factor and matrix metalloproteinases and are effective in bleomycin‐induced lung fibrosis." (PMID 28186707, 2017). "TGF-β1 induction and lung fibrosis were shown to be abolished by HGF." (PMID 25954275, 2015). "Furthermore, MSCs-based HGF gene therapy reduces inflammation and inhibits lung fibrosis in a radiation-induced lung injury model." (PMID 25933295, 2015). "Moreover, HGF-expressing BMSC significantly reduced bleomycin induced lung fibrosis as shown by hydroxyproline assay, Ashcroft score and stereological data analysis." (PMID 23840329, 2013). "Our data indicate that both pluripotent stem cells and HGF may have a beneficial effect in lung fibrosis and may represent the basis of a novel therapeutic approach for patients suffering from UIP/IPF." (PMID 23840329, 2013). "Recent publications showed defective HGF production and secretion by fibroblasts obtained from patients with IPF, indicating that low levels of HGF in the fibrotic lung may contribute to the development of lung fibrosis." (PMID 23840329, 2013). "In this respect, HGF may present the basis of a promising novel strategy for the treatment of pulmonary fibrosis." (PMID 23840329, 2013). "Furthermore, HGF gene transfection prevented the symptoms of not only dermal sclerosis, but also lung fibrosis induced by bleomycin injection." (PMID 17049072, 2006). "Owing to few studies that have depicted the influence of HGF modification on UCMSCs, we conducted mRNA sequencing to uncover the transcriptional change of transfecting Ad-HGF into UCMSCs, thereby ascertaining whether HGF alone participates in treating pulmonary fibrosis." (PMID 36726784, 2022). "Moreover, HGF was reported to have the function of suppressing lung fibrosis." (PMID 33747095, 2021). "However, HGF has also been shown to protect against pulmonary fibrosis." (PMID 33119677, 2020). "HGF is an important growth factor and plays a major role in lung development in the early embryonic stages, specifically by regulating epithelial development and efficient branching morphogenesis, and also latter in the adult lung and in various disease processes including pulmonary fibrosis." (PMID 25384638, 2014). "Moreover, high levels of HGF were identified in iPSC-cm, and in the presence of HGF neutralizing antibody the effect of iPSCs on alveolar epithelial wound repair in vitro and reduction of lung fibrosis in the bleomycin model was in part abolished." (PMID 25384638, 2014). "Key overlapping canonical pathways included the Senescence Pathway, Idiopathic Pulmonary Fibrosis Signaling, ERK5 Signaling, RHO GTPase Cycle, and HGF Signaling." (PMID 40734983, 2025). "Hypoxic preconditioning of MSCs prior to transplantation showed to result in improved protection from pulmonary fibrosis, at least partially, via increased production of VEGF and HGF." (PMID 38886859, 2024). "Thus, HGF-UCMSCs may ameliorate pulmonary fibrosis by inhibiting IL-17 in the lung." (PMID 36726784, 2022). "For example, hepatocyte growth factor (HGF)-modified Ad-HGF-MSC showed a better ability to reduce expression of inflammatory cytokines, thereby protecting ATII cells and inhibiting pulmonary fibrosis." (PMID 36611801, 2022). "In another study that focused on iPSC secretome, the culture medium containing hepatocyte growth factor (HGF) secreted by iPSCs contributed to AECs repair in vitro and attenuated BLM-induced lung fibrosis in vivo." (PMID 34685439, 2021). "By detecting HGF and MMP-9, we have provided a potential target for ERCs to alleviate lung fibrosis." (PMID 30147727, 2018).
lung fibrosis (continued). "In murine models, overexpression of hepatocyte growth factor (HGF) and inhibition of profibrotic NADPH oxidase 4 (NOX4) in VECs creates a modified vascular microenvironment in the liver and lung tissue that promotes liver and lung fibrosis." (PMID 40114970, 2025). "Involved mediators in lung fibrosis, such as interleukin 6 (IL-6), vascular endothelial growth factor (VEGF) and hepatocyte growth factor (HGF), are produced by fibroblasts and may induce both pro- and antifibrotic events in the alveolar regions." (PMID 33419174, 2021). "One caveat of this study is that HGF levels are increased in fibroblasts from ILD patients, which is contradictory to the finding that HGF negatively regulates TGF-β1 induction, and therefore inhibits lung fibrosis." (PMID 25954275, 2015). "In particular, microRNA regulation of genes of hepatocyte growth factor-, endothelin-1- or IGF1- signaling, and specific molecular mechanisms of cancer, may affect lung fibrosis." (PMID 23987664, 2013). "In contrast, the increased expression of HGF in clinical samples, for example, bronchoalveolar lavage fluid and serum, was positively correlated with IPF severity, suggesting that the potential local protective mechanism of HGF does not effectively prevent the progression of pulmonary fibrosis." (PMID 41244106, 2025). "Many factors are involved in the development of pulmonary fibrosis including transforming growth factor-beta (TGF-β), vascular endothelial growth factor (VEGF), platelet-derived growth factor (PDGF), fibroblast growth factor (FGF), and hepatocyte growth factor (HGF)." (PMID 38970048, 2024). "Thus, in vitro and in vivo experiments are needed to confirm whether IL-17-producing cells are the targets of HGF and whether IGFBP5 and SCRG1 participate in the treatment of pulmonary fibrosis." (PMID 36726784, 2022). "Transduction of MSC with IL-10 or HGF prevented lung fibrosis after MSC application as both paracrine factors are able to control the unwanted release of TGF-β1 by MSC, which accounted for the tremendous increase in lung fibrosis after naïve MSC transplantation." (PMID 32138309, 2020). "Taken together, these data provide in vivo evidence that enhanced PGE2, PGD2, and HGF secretion in alveolar macrophages following apoptotic cell instillation protects against the EMT phenotype in AT II cells and fibroblast activation in murine bleomycin-induced lung fibrosis." (PMID 26875548, 2016). "Though the statistical difference was not present between the UCMSC and HGF-UCMSC groups, it is likely that HGF modification probably promoted the anti-fibrotic effect of UCMSCs in bleomycin-induced pulmonary fibrosis." (PMID 36726784, 2022). "Since HGF-expressing, CXCR4+ cells in UIP did neither co-stain with vimentin nor with α-SMA, we assume that these cells are not fibrocytes that were recently described to play a major role in the pathogenesis of pulmonary fibrosis." (PMID 23840329, 2013).
diabetes (54 papers, 2007 to 2026). "The importance of fatty liver was particularly striking among the top 30 diabetes-associated proteins (e.g. HGF, IGSF3, IL1RA, ALDH1A1, HNMT, ERBB2 and CDCP1)." (PMID 33279861, 2021). "Hepatocyte growth factor has been associated with incident type 2 diabetes, and endothelial cell specific molecule 1, with atherosclerosis in subjects with diabetes." (PMID 30237882, 2018). "However, clinical studies report that circulating HGF level is associated with stroke risk factors involved in endothelial dysfunction, including hypertension, diabetes mellitus, smoking, and age." (PMID 34421795, 2021). "The protein FUR has previously been studied in depth in MDC-CC and found to be strongly associated with diabetes incidence, and HGF plays a role in both hepatic glucose and lipid metabolism, and in the development of insulin resistance, fatty liver disease, cardiovascular diseases and cancers." (PMID 33066363, 2020). "For instance, in the study among post-menopausal women, participants in the highest tertile for serum HGF concentrations had a 2.4-fold (95% CI1.12–5.47) higher risk for prevalent diabetes compared with participants in the lowest tertile for serum HGF concentrations." (PMID 27158627, 2015). "This study elucidates a novel mechanism by which KLK8 upregulation contributes to diabetes-induced microglial activation and neuroinflammation in the hippocampus through modulating the hepatocyte growth factor (HGF)/Met signaling pathway." (PMID 40521191, 2025). "The HGF-Met system is instrumental in hepatic metabolism and enhancing insulin sensitivity in animal diabetes models." (PMID 38654922, 2024). "HGF has anti-inflammatory properties; it can increase IL-10 levels and reduce IL-1β levels in pancreatitis or diabetes." (PMID 38533089, 2024). "One study measured elevated HGF levels in the retinas of mice with STZ-induced diabetes and showed that HGF supplementation improved pericyte survival after TNFα stimulation, suggesting potential relevance of HGF in vascular permeability in DR." (PMID 39716241, 2024). "As previously discussed, hepatocyte growth factor (HGF) is pivotal in the development of type 2 diabetes mellitus (DM), serving as a significant inhibitor of hepatic glucose production in individuals with insulin resistance." (PMID 38654922, 2024). "It was shown that the use of pIRES/VEGF165/HGF plasmid in patients with lower limb ischemia and diabetes significantly improved vascularization of the affected limb." (PMID 39194724, 2024). "In logistic regression models, RBP-4, Col1,and HGF were associated with increased albuminuria(UACR ≥ 3.0 mg/mmol) after adjustment for age, sex, BMI, duration of diabetes, and HbA1C." (PMID 36836700, 2023). "Intramuscular injections of HGF have also been successful for treatment of models of streptozocin-induced diabetes and crush injury." (PMID 32780756, 2020). "The data showed that compared with the control group, the expression levels of CASP3, VCAM-1 and HGF were down-regulated in patients with syphilis and diabetes, while ALB, FN1, MMP9, IL8, CTGF, STAT3 and IGF1 were up-regulated." (PMID 32342229, 2020). "HGF plays a central role in metabolic disorders such as insulin resistance and in diabetes pathophysiology." (PMID 31355136, 2019). "Higher levels of HGF were significantly associated with both CIND and AD after correction for age, gender, APOE ε4 carrier, hypertension, diabetes, and cardiovascular diseases." (PMID 29410622, 2018). "Following this line of reasoning, it was shown in hyperglycemia/diabetes, induced by stressful situations, that HGF has a protective role in physiological status of β-cells." (PMID 30214428, 2018). "This review discusses the significance of each of these five HGF features in the pathophysiology of IR and diabetes and presents evidence for HGF in the etiology of cancer." (PMID 30214428, 2018).
diabetes (continued). "In this review, we discuss how, and to what extent HGF contributes to IR and diabetes pathophysiology, as well as its role in cancer which is more prevalent in obesity and diabetes." (PMID 30214428, 2018). "In humans, it has been demonstrated that levels of circulating HGF are elevated in obesity, metabolic syndrome, and diabetes mellitus." (PMID 30214428, 2018). "The MAP kinase pathway is implicated in the regulation of retinal vascular permeability by hepatocyte growth factor in diabetes, and also in glucose-induced apoptosis of retinal endothelial cells." (PMID 23675062, 2008). "In diabetes, regulation of retinal vascular permeability by hepatocyte growth factor is considered to be mediated via MAP kinase pathway, and glucose has been shown to accelerate apoptosis of retinal endothelial cells via activation of MAP kinase." (PMID 17515880, 2007). "Additionally, research has revealed elevated circulating levels of HGF in conditions such as obesity, metabolic syndrome, and diabetes mellitus." (PMID 40076884, 2025). "Inactivation of the HGF/Met signaling pathway might be an effective strategy to inhibit microglia activation and neuroinflammation during diabetes." (PMID 40521191, 2025). "Our results also revealed that another five proteins (HGF, CD6, fibroblast growth factor 21 (FGF-21), LIF-R, and OSM) might mediate the associations of gut bacteria with diabetes." (PMID 38643166, 2024). "A statistically significant positive correlation was found between serum glucose values and HGF concentration only in the UAH group, and as previously stated, other studies also found higher HGF concentrations in diabetics, especially those with pronounced atherosclerotic changes and retinopathy." (PMID 39457546, 2024). "Thus, evaluating the effectiveness and practicality of HGF in the clinical management of Diabetes mellitus is essential." (PMID 38654922, 2024). "Likewise, higher serum levels of HGF have been found in individuals with cardiovascular disease (CVD) risk factors e.g., smoking, obesity, hypertension and diabetes." (PMID 35047572, 2021). "However, participants with diabetes showed increased expression of 9 proteins, such as IL-6 and HGF." (PMID 34385358, 2021). "It has been reported that HGF may have protective effects against insulin resistance by allowing for regeneration of β cells in diabetes mellitus." (PMID 32517700, 2020). "Thus, further emphasizing the role of HGF in the pathophysiological processes of obesity/IR/diabetes." (PMID 30214428, 2018). "Taken together, these findings indicate that HGF could be employed as a regenerative factor in the treatment of diabetes." (PMID 30214428, 2018). "In fact, innovative mechanisms for controlling HGF expression and/or activity could generate unique therapies for the treatment of IR and diabetes." (PMID 30214428, 2018). "However, the mechanism of HGF-mediated antifibrosis effect, specifically in diabetes is poorly understood." (PMID 23560074, 2013). "Moreover, patients with type 2 diabetes have higher concentrations of HGF when they have diabetic retinopathy, and the measurement of serum HGF could be useful in predicting the presence of diabetes complications." (PMID 39457546, 2024). "Similarly, CD14+DN cells from patients with diabetes produced significantly less IL-8 (P < 0.05 for comparison to NoDR; P < 0.001 for DR patients), while HGF and IL-3 secretion was only significantly less in the DR group (P < 0.001, and P < 0.01, respectively)." (PMID 38983045, 2023). "HGF binds to c-Met in the plasma membrane, activates the AKT/mTOR signalling pathway, plays a vital role in cell growth, metabolism, cell survival and migration; in addition, HGF is closely associated with developmental defects, cancer, diabetes and autoimmune diseases." (PMID 32795289, 2020).
diabetes (continued). "In context of MMD, patients with diabetes may elevate expression of growth factors and cytokines, such as hepatocyte growth factor, transforming growth factor-β, vascular endothelial growth factor, and nitrotyrosine, which could lead to more collateral angiogenesis." (PMID 31092214, 2019). "In this observational study, we aimed to identify correlations between serum levels of HGF and EGF, insulin, glucagon, glucose, and primary serum lipids in patients with type 2 diabetes mellitus (DM), taking into account the impact of gender." (PMID 38654922, 2024). "Clinical parameters and serum levels of HGF, EGF, insulin, and nitrogen-related compounds in control subjects and patients with Type 2 Diabetes Mellitus, with results expressed as medians." (PMID 38654922, 2024). "Of note, the contributions of HGF and OSM to insulin resistance and glucose impairment in obesity and diabetes have reported, and elevated levels of LIF-R have been noted in hepatic steatosis and MAFLD-associated gut dysbiosis." (PMID 38643166, 2024). "Compared to individuals with high HGF, a greater proportion of patients with low HGF had PAD (76% vs 34%, p = 0.001) and diabetes (40% vs 28%, p = 0.020)." (PMID 37809892, 2023). "The present study aimed to test HGF/VEGF combined plasmid efficacy in ischemic skeletal muscle comorbid with predominant complications of PAD-impaired glucose tolerance and type 2 diabetes mellitus (T2DM)." (PMID 36497083, 2022). "In total there were 44 out of 973 (4.5%) proteins that contributed significantly to the prediction of diabetes (FDR-corrected p<0.05) in the random forest model, the most important being NOS3, HGF, PON3, IGSF3, and ADGRG1." (PMID 33279861, 2021). "HGF enhances the neo-epithelialization via the β1-integrin/ILK pathway, and its exogenous administration improves the wound healing in diabetes mellitus in mice." (PMID 34445365, 2021). "We also found that diabetes was related to increased expression of nine proteins, IL-18R1, CCL11, CDCP1, OPG, HGF, TGF-α, CCL20, IL-6 and FGF-21." (PMID 34385358, 2021). "Hence, examining EV HGF content may provide more knowledge on the biological mechanisms that counteract insulin resistance and elucidate the complex role EVs play in individuals with diabetes." (PMID 32517700, 2020). "Thus, HGF levels could be employed as a biomarker for disease status/progression, and HGF/c-Met signaling pathway modulators could effectively regulate IR and treat diabetes." (PMID 30214428, 2018). "After controlling for baseline variables including sex, age, dyslipidemia, hypertension, smoking status (past or current), diabetes, CAD, CHF, and prior stroke, both HGF and angiopoietin-2 plasma levels remained independently associated with the occurrence of MACE at 2 years." (PMID 40565778, 2025). "The concentration of serum HGF in subjects with type 2 diabetes was significantly higher than in healthy control subjects, even when the subjects with diabetes did not have AH." (PMID 39457546, 2024). "Notably, associations of Ruminococcus, Adlercreutzia, and Escherichia with diabetes were mediated considerably by multiple inflammatory proteins led by OPG, IL-18R1, and HGF." (PMID 38643166, 2024). "Conversely, healthy men and women with diabetes demonstrated weak and negative correlations (rho coefficients of −0.2777 and −0.2639, respectively) between insulin and HGF." (PMID 38654922, 2024). "We then tested whether adding plasma HGF to the conventional model (including age, NIHSS score, diabetes, and t-PA treatment) could improve the predictive ability for unfavorable outcomes in patients with AIS." (PMID 34421795, 2021). "In this previous study, we demonstrated that diabetes-induced ER stress in AMs suppresses HGF production but that efferocytosis is not significantly affected." (PMID 32724133, 2020).
diabetes (continued). "Given the strong correlation between diabetes and cardiac fibrosis, we explored whether BMPC therapy (via HGF secretion) inhibits miR-155 expression and prevents cardiac fibrosis in the infarcted hearts of diabetic mice." (PMID 23560074, 2013). "Crude odds ratio estimates remained within the range of 1.5–2.0 and 2.0–2.5 range for LTA4H and HGF, respectively, when stratifying for time to death from first symptom onset, time-to-event, ECG classification, chronic coronary syndrome medication, and diabetes status." (PMID 36142157, 2022). "In addition to stimulation of angiogenesis, the combination of HGF and VEGF165 may have a positive pleiotropic influence of peripheral nerve function known to be impaired in limb ischemia and diabetes." (PMID 33353116, 2020).